MYCN (MYCN proto-oncogene, bHLH transcription factor)
Diseases named in the same sentence as MYCN in open-access papers (continued):
Sharing a sentence is not in itself a finding about the gene and the disease.
tumor (continued). "MYCN is a member of the MYC family of transcription factors and encodes the N-myc proto-oncogene protein which regulates various pathways affecting cell survival, tumorigenesis, tumor progression and metastasis development." (PMID 35163370, 2022). "A maximum primary tumor diameter > 13.20 cm and MYCN gene amplification were two independent risk factors for high-risk NB tumor rupture." (PMID 33387076, 2021). "Current NB risk stratification is mainly based on an assessment of clinical data, tumor histology, and genetic aberrations, such as MYCN-amplification (20% of all NB and 50% of high-risk NB) and 11q aberrations (20–45% of all NB)." (PMID 34556815, 2021). "CHD5 has been proposed as a distal tumour suppressor, involved in smaller 1p36 deletions associated with MYCN single-copy NB and MYCN-amplified NB." (PMID 34884690, 2021). "Combination therapy with the CDK7 (super-enhancer) inhibitor THZ1 and the histone deacetylase inhibitor panobinostat synergistically reduces JMJD6, E2F2 and MYCN expression, inducing apoptosis in vitro and causing NB tumor regression in mice." (PMID 34945759, 2021). "The univariate analysis showed that the five-gene risk score (p < 0.0001), tumor histology (p < 0.0001), age (p = 0.00065), and MYCN status (p = 0.024) were associated with the prognosis of NB." (PMID 34950701, 2021). "On one hand, it is the cause of tumor growth under nutrient-deprived conditions whose adaptation promotes NB progression; on other hand, abnormal expression of MYCN leads to the direct activation of cell death pathways." (PMID 34011924, 2021). "High levels of Bcl-2 expression have also been correlated with tumor severity, which is associated with unfavorable histology, MYCN amplification, and poor prognosis." (PMID 34832966, 2021). "This tumor is associated with several genetic and chromosomal abnormalities that affect its clinical course and prognosis namely MYCN amplification, loss of distal portion of chromosome (chr) 1p and gain of 17q." (PMID 33718173, 2021). "Subsequently, a separate report indicated that six of eight tumours with MYCN amplifications also contained at least one RB1 mutation." (PMID 33670346, 2021). "We identified MEIS2 as an early tumor initiation associated factor, as well as multiple novel MYCN-upregulated dependency genes." (PMID 34638267, 2021). "Of note, amplification of the MYCN oncogene is associated with an aggressive NB tumor behavior and poor outcome." (PMID 33712610, 2021). "These tumor organoids originate from high-risk tumors containing 1p loss, MYCN amplification, and 17q gain and are tumorigenic upon implantation in vivo." (PMID 34118691, 2021). "Aberrant expression of MYCN has been associated with tumor aggressiveness, resistance to chemotherapy, and the inability to differentiate." (PMID 33724150, 2021). "Mouse models of retinoblastoma and neuroblastoma show that Rb1 loss in MYCN-driven tumors accelerates tumor progression and shortens survival time." (PMID 34099734, 2021). "While MYCN promotes cell cycle progression and other features of aggressive tumor growth, NTRK1 induces differentiation and is associated with excellent patient outcome." (PMID 34771457, 2021). "MYC and MYCN amplifications especially are prominent in MB due to the highly aggressive nature of tumours associated with these aberrations." (PMID 34195095, 2021). "MYC and MYCN amplifications in particular have been the main focus in MB due to the highly aggressive nature of tumours associated with these aberrations." (PMID 34195095, 2021). "In vivo, rigosertib treatment of a high-risk MYCN-amplified PDX model delayed tumor growth and prolonged survival." (PMID 34118691, 2021). "In general, risk groups are based on patient age, the INRGSS system, tumour histology/differentiation, tumour ploidity and segmental chromosome aberrations, and the presence of MYCN amplifications." (PMID 34575503, 2021).
tumor (continued). "MYCN focal gain is a well-established prognostic factor for high-risk cases, marked by advanced tumour stage, high aggressiveness, and poor outcome." (PMID 34884690, 2021). "This was verified by MSAI events on chromosome 9q, allele-specific LOH or MYCN amplifications that differed between the metastases and matched primary tumours." (PMID 34815394, 2021). "Patients with stage 4 tumours have poor outcomes and 20% of high-risk cases have MYCN amplification." (PMID 32714600, 2020). "High expression of MYCN is usually associated with highly proliferative potential of tumor cells and dismal prognosis." (PMID 32907612, 2020). "Taken together, the data establish that the in vivo activity of CYC065 against MYCN-dependent NB tumor progression proceeds largely through transcriptional depletion of MYCN, leading to increased apoptosis and rapid loss of tumor burden." (PMID 33016930, 2020). "Both cases can be therapeutically relevant since we both seek to suppress signatures associated with risk (like MYCN) and enhance signatures likely to be associated with slower tumour growth (like differentiation)." (PMID 31900415, 2020). "According to the International NB Staging Series (INSS), which relies on surgical observations, NB is classified by risk level, tumor location and dissemination, and MYCN (proto-oncogene protein) amplification." (PMID 32155795, 2020). "Studies have demonstrated that high expression/amplification of MYCN is associated with increased energy metabolism, rapid tumor growth, short survival rates, unfavorable histology, and chemotherapy resistance in NB patients." (PMID 31637848, 2020). "NB patients are stratified into low-, intermediate- and high-risk groups, based on different parameters, including tumor histology, clinical stage, tumor cell ploidy, and MYCN oncogene amplification." (PMID 32722460, 2020). "As with the previous in vitro studies, we observed increases in caspase-3 and PARP cleavage concomitant with MYCN loss in both Kelly NB tumor xenografts and TH-MYCN tumors following treatment with CYC065." (PMID 33016930, 2020). "It was shown that the expression of ABCC4 was associated with MYCN amplifications as well as advanced tumor stage." (PMID 32587767, 2020). "Doxycycline-induced overexpression of MYCN in ATRX-mutant NB cell lines showed a marked loss of tumor cells." (PMID 33628735, 2020). "In MYCN-amplified Kelly NB tumor xenografts, we observed rapid loss of MYCN protein, induction of apoptosis, and decreased RNAPII Ser2P." (PMID 33016930, 2020). "For both patient A6580 and patient A6912, xenografted tumours at each site were highly correlated with the patient sample, including conservation of MYCN and ALK amplification, chromosome 1p loss and chromosome 17q gain in each." (PMID 31919402, 2020). "Association between CASP8 methylation and known risk factors such as MYCN amplification, tumor stage, and age at diagnosis was studied in previous studies." (PMID 33381579, 2020). "Despite the limited amount of CSF cfDNA, mutations and most relevant genomic alterations identified in the tumour were also detected in the CSF ctDNA, including MYCN and GLI2 amplification, and partial loss of 17p." (PMID 33110059, 2020). "According to multivariate logistic regression analysis, a maximum primary tumor diameter > 13.20 cm and MYCN gene amplification were independent risk factors for tumor rupture within high-risk NB." (PMID 32293329, 2020). "It is well known that MYCN causes downregulation of major histocompatibility complex (MHC) class I antigen expression in NB that contributes to tumor antigen presentation and is necessary for the initiation of an immune attack." (PMID 33050533, 2020).
tumor (continued). "Specifically, we propose CX-5461 will have efficacy in HR-deficient HGSOC and in HGSOC tumours with elevated MYC activity such as the high-MYCN HGSOC subtype associated with poor prognosis." (PMID 32457376, 2020). "Although genomic amplification of MYCN was the common genetic aberration consistently associated with poor prognosis and was deemed the vital marker for tumour recurrence and malignancy in NB, it was only detected in less than 30% of all NB cases." (PMID 31511046, 2019). "Genomic amplification of the MYCN oncogene is associated with NB tumour aggressiveness and poor prognosis in NB patients." (PMID 30914706, 2019). "Genomic amplification of MYCN is reported in around 25% of NB tumours (approx. 40% among high-risk patients) and is generally accepted as the strongest predictor of poor prognosis and rapid tumour progression." (PMID 31088252, 2019). "While the ALK associated lincRNA was also expressed in NB cell lines, expression of up to 11% of MYCN associated lincRNAs was restricted to NB tumor samples." (PMID 30952905, 2019). "The percentage of stage 4 patients with MYCN amplification is around 30%, and in high-risk disease, this is slightly higher because of localised MYCN amplified tumours being included." (PMID 30822684, 2019). "Many known oncogenic and tumour-suppressive miRNAs have been shown to be aberrantly expressed in primary NB tumours, with a particular focus on those targeting MYCN among other genes implicated in NB pathogenesis." (PMID 31088252, 2019). "Correlation with tumour pathology and risk factors (bone-marrow metastases, MYCN-amplification and 1p-deletion), therapeutic regime (observation versus chemotherapy) and clinical follow-up was evaluated." (PMID 30701332, 2019). "In this study, we comparatively analyzed the transcriptomes of Casp2−/− tumors from EμMyc and Th-MYCN mice to identify changes in transcriptional tumor networks that are influenced by caspase-2 deficiency." (PMID 30670683, 2019). "By opposite, in malignancies including NB, aberrant amplification and/or overexpression of MYCN have been associated with tumor aggressiveness with MYCN-amplified cells having stem like characteristics and a pluripotent state." (PMID 31040907, 2019). "Inhibition of CDK7 or CDK9 selectively kills tumor cells, by targeting the super-enhancer clusters of the genome that are associated with MYCN regulation." (PMID 35582571, 2019). "In one Th-MYCN driven tumor, a bi-allelic Dicer1 missense mutation known to affect the activity of the RNAse III domain was observed, reducing 5p end processing of pre-miRs including reduced levels of miRNAs of the let-7 family." (PMID 29492199, 2018). "Amplified MYCN is strongly associated with advanced, aggressive tumours and frequent disease relapse." (PMID 29642598, 2018). "NB patients are subdivided into low-, intermediate-, and high-risk groups based on clinical stage, age at diagnosis, tumor histology, MYCN oncogene amplification, histology, and chromosomal ploidy." (PMID 29682521, 2018). "In the present series 7% of tumours were found to carry the mutation, further supporting a role of aberrant activation of MYCN in WT." (PMID 30344923, 2018).
tumor (continued). "The Th-MYCN driven tumor which harbors this mutation is showing a total of 6 mutations of which 2 are non-synonymous (the second one in an olfactory receptor gene, likely a passenger mutation)." (PMID 29492199, 2018). "The LIN28B situated on the LIN28B-let-7-MYCN axis, can downregulate let-7, a tumour suppressor miRNA family that causes an up-regulation of MYCN, resulting in NB growth stimulation." (PMID 29315268, 2018). "MYC genes, most commonly MYC and MYCN, are frequently amplified in MB and are associated with a poor prognosis and/or tumor recurrence." (PMID 29511348, 2018). "Its unique presentation and tumor biology present challenges for effective treatment regimens, notably in patients diagnosed as high risk (>MYCN expression)." (PMID 29751783, 2018). "In clinical medicine, patients with MYCN-amplified SCLC have been associated with tumor aggressiveness and shorter survival." (PMID 29156797, 2017). "Mutations in these enzymes also impaired the expression of tumour suppressor miRNAs such as the let-7 family; this is an important regulator of genes such as MYCN, LIN28 as well as other previously identified WT oncogenes." (PMID 28103887, 2017). "This is in contrast to the second case of a young child with a MYCN-amplified tumor that was associated with diffuse bone marrow involvement at presentation." (PMID 28864906, 2017). "It has been suggested that MYCN amplification is strongly associated with rapid tumor progression and poor prognosis." (PMID 28465480, 2017). "In neuroblastoma MYCN amplification (MYCNA) is associated with the classical hallmarks of tumor progression and metastasis, such as adhesion, motility and tissue invasion." (PMID 29124525, 2017). "Irrespective of all other clinical, molecular, or biomarkers, if MYCN is amplified in the tumor it is categorized as high risk." (PMID 29163537, 2017). "Tumours with amplification of the MYCN transcription factor and/or loss of the distal chromosome 1p and gain of 17q are a major genetic subtype of metastatic NB that has a particularly poor prognosis (known as MNA)." (PMID 28103887, 2017). "Low miR-497 expression was associated with shorter event-free survival and MYCN amplification in our cohort of human NB samples, suggesting a tumor-suppressor role." (PMID 26824183, 2016). "Taken together, these data suggest that FZD2 blockade reduces tumor growth and tumor cell proliferation associated with decreased β-catenin levels and reduced angiogenesis in both, MYCN-unamplified SK-N-AS and MYCN-amplified SK-N-DZ NBs." (PMID 27323822, 2016). "The detection of heterogeneous MYCN amplification (hetMNA) poses a diagnostic dilemma due to the uncertainty of its relevance to tumor behavior." (PMID 26910568, 2016). "The lncRNA, mycn opposite strand (MYCNOS) physically interacts with a transcription factor CCTF and epigenetically enhances MYCN expression resulting in loss of differentiation, tumor progression and invasion in NB cells." (PMID 27517149, 2016). "Immunohistochemical analysis showed that tumor regression induced by MYCN withdrawal correlated with the loss of expression of the Ki67 proliferation marker." (PMID 25785590, 2015). "To determine the proportion of WTs harbouring this or other MYCN mutations in a larger, unselected cohort, we sequenced the complete MYCN coding region in 168 additional tumour samples." (PMID 25749049, 2015). "MYCN gene amplification, found in 50% of high-risk patients, is associated with rapid tumour progression and a poor prognosis." (PMID 25844600, 2015). "Univariate class comparisons (two-sample t-test) between the IR tumours (taken together as a group) and the tumours in either of the high risk groups identified MYCN as a relatively overexpressed gene in both DA and BT WT." (PMID 25749049, 2015). "High levels of SLC19A1 mRNA expression were significantly associated with MYCN amplification in both cohorts (Fisher's exact, P = 0.015 and P < 0.001 for the 42 and 650 tumor cohorts, respectively)." (PMID 25860940, 2015).
tumor (continued). "Early genetic studies into NB revealed some large-scale chromosomal rearrangements and amplifications in some tumours; most notably MYCN amplification was found to be consistently associated with poor prognosis in NB." (PMID 25786414, 2015). "In a whole exome analysis of a series of 51 WTs, enriched in cases with high risk histology or poor outcome, heterozygous somatic point mutations in the MYCN coding sequence were detected in three tumours." (PMID 25749049, 2015). "In this study, barasertib caused profound inhibition of tumor growth in MYCN-amplified IMR32 xenografts." (PMID 26497213, 2015). "MYCN was relatively overexpressed in diffuse anaplastic and blastemal type tumours, and there was an association between expression level and poorer relapse-free survival." (PMID 25749049, 2015). "Approximately half of high-risk NBs exhibit MYCN amplification, which is associated with older age, rapid tumor progression and the poorest prognosis." (PMID 24190252, 2014). "In a MYCN transgenic context, the F1178L mutation displays a higher oncogenic potential than the R1279Q mutation as evident from a shorter latency of tumor onset." (PMID 24811913, 2014). "MYCN amplification found in about 20 % of primary NBs is associated with rapid tumor progression and poor prognosis." (PMID 24515800, 2014). "MYCN amplification has been shown to be strongly associated with rapid tumor progression and poor prognosis in patients of all ages, independent of the stage of disease (with the exception of stage 1)." (PMID 25161957, 2014). "We now show that both F1178L and R1279Q Alk mutations accelerate tumor onset and increase tumor penetrance in a MYCN context." (PMID 24811913, 2014). "The expression level of MYCN has also been shown to be correlated with the activation of genes associated with tumor aggression." (PMID 24586395, 2014). "The paper by the Pistoia’s team describes the possible role of MYCN as a tumor-associated antigen and strategies to generate cytotoxic T cells directed against pediatric tumors expressing the oncogene." (PMID 26029658, 2014). "Patients have been traditionally risk-stratified according to tumor-associated biologic factors including MYCN gene amplification, DNA ploidy, and loss of heterozygosity (LOH) of chromosomes 1p and 11q." (PMID 24349301, 2013). "Supporting this, our results demonstrated that low expression of KRT19 was significantly associated with high tumor stages, MYCN amplification and an unfavorable outcome in NB." (PMID 23135478, 2013). "A recent international review of 8,800 patients throughout 1990–2002 confirmed patient age at diagnosis, tumor stage, DNA ploidy, chromosome 11q status, and MYCN status as important parameters to consider for patient risk stratification." (PMID 23267433, 2012). "As expected significant associations were apparent between tumor stage vs. MYCN amplification; vs. 1p loss; and vs. high-risk, as well as between MYCN amplification vs. 1p loss and vs. high risk." (PMID 22984959, 2012). "A number of clinical features and tumor phenotypes influence the disease outcome; the most important are age at diagnosis, tumor stage, amplification of the MYCN oncogene, activating ALK mutations, and somatic loss within chromosomal region 1p." (PMID 22984959, 2012). "In both studies, ABCC4 expression was associated with MYCN amplification as well as advanced tumor stage." (PMID 23267433, 2012).